HOXD11 (homeobox D11)
Diseases named in the same sentence as HOXD11 in open-access papers (continued):
Sharing a sentence is not in itself a finding about the gene and the disease.
sarcoma (1 paper, 2025). A usually aggressive malignant neoplasm of the soft tissue or bone. "Several of the identified MLS- and EWS-specific transcription factors are implicated in FET sarcoma oncogenesis; for example, increased gene expression of the EWS-specific transcription factors HOXD11, SOX6, MEIS1, and E2F6 were reported to be involved in EWS malignancy." (PMID 40988026, 2025).
tumor (19 papers, 2012 to 2025). "Taken together, we demonstrated that the HOXD11/FN1/MMP2/MMP9 axis was an underlying molecular mechanism promoting tumor invasion and metastasis via an EMT-like phenotype in PSCC." (PMID 36151071, 2022). "Consequently, we clarified the functional role of HOXD11 in tumor progression and metastasis and explored the underlying molecular mechanisms." (PMID 36151071, 2022). "HOXD11 acts as a kind of tumor suppressor, while miR-138-5p can promote tumor malignant progression in PSCC by binding to the 3' non translated region to inhibit HOXD11 post-transcriptional translation and promote malignant tumor progression." (PMID 40657383, 2025). "Recent studies have shown that HOXD11 is involved in tumor development and helps control gene expression." (PMID 36251702, 2022). "These genes have been associated with tumour suppression (BRCA1 and FAT1), DNA repair (POLE), morphogenesis (HOXD11), epigenetic regulation (WHSC1), lipid metabolism (PPARG) and red blood cell development (GATA1)." (PMID 36131292, 2022). "The GO enrichment and KEGG pathway analyses showed that the biological function of tumor metastasis via epithelial mesenchymal transition (EMT) was significantly enriched when HOXD11 was inhibited in PSCC." (PMID 36151071, 2022). "Further mechanistic studies indicated that miR-138-5p was a tumor suppressor in PSCC by inhibiting the translation of HOXD11 post-transcriptionally through binding to the 3′ untranslated region." (PMID 36151071, 2022). "HOXD11, located at chromosome 2q31.1, is involved in neoplastic transformation, especially the processes of tumor invasion and metastasis, in previous studies." (PMID 36151071, 2022). "Similar to previous findings, HOXD11 knockdown or overexpression inhibited or promoted colony formation, cell proliferation, migration and invasion in vitro and subcutaneous tumor growth in vivo." (PMID 36151071, 2022). "We demonstrated that HOXD11 is a novel therapeutic target mediated by miR-138-5p promoting tumor metastasis of PSCC via the FN1/MMP2/MMP9 molecular pathway." (PMID 36151071, 2022). "Numerous studies have shown that HOXD11 is involved in tumor development and that it helps regulate gene expression." (PMID 33614284, 2021). "After serial sectioning, we observed that A673 sh.HOXD10 and sh.control tumor nodules in lungs were bigger with a higher amount of necrosis than the tumor nodules after injection of A673 cells with stable HOXD11 and HOXD13 knock down." (PMID 27363011, 2016). "A673 control infectants grew to numerous confluent and necrotic tumor nodules within the lung, while A673 sh.HOXD11 and A673 sh.HOXD13 infectants revealed a significantly reduced metastatic phenotype that was statistically significant (right)." (PMID 27363011, 2016). "Especially after injection of constitutive A673 sh.HOXD10 and sh.HOXD11 transfectants, the amount of tumor cells in the bone marrow was clearly reduced." (PMID 27363011, 2016). "HOXA5, HOXD10 and HOXD11 showed the highest expression levels and their up-regulation was then validated by qRT-PCR in tumor samples as well as in cell lines." (PMID 22227861, 2012). "Moreover, HOXC8, HOXD10, and HOXD11 were confirmed to be involved in biological processes related to tumor formation and progression, such as clone formation and cell metastasis." (PMID 36718148, 2023). "MiR-138-5p served as a tumor suppressor inhibiting the HOXD11-mediated progression of PSCC." (PMID 36151071, 2022). "Furthermore, tumorigenesis assays demonstrated that knockdown of HOXD11 not only inhibited the capability of cell proliferation, invasion and tumor growth but also reduced the burden of metastatic lymph nodes." (PMID 36151071, 2022). "Moreover, the expression of MMP2 and MMP9 was reversed when FN1 expression was knocked down in HOXD11-overexpressing cells, which suggested the indispensable role of FN1 in HOXD11-mediated tumor progression." (PMID 36151071, 2022).
tumor (continued). "Therefore, our results demonstrated that knockdown of HOXD11 impaired tumor growth and lymph node metastasis in vivo." (PMID 36151071, 2022). "To identify the role of HOX genes cluster in the progression of PSCC, we performed qPCR with a panel of 34 HOX genes in 12 paired PSCC patients, including normal, primary tumor and metastatic lymph node tissues, and determined that HOXD11 was upregulated and involved in tumor metastasis." (PMID 36151071, 2022). "Our results demonstrated that HOXD11 directly bound to FN1 promoter regions and promoted the expression of FN1, which is a vital component of ECM in shaping the tumor microenvironment to promote metastasis." (PMID 36151071, 2022). "Further qPCR, WB and IHC assays confirmed that HOXD11 was overexpressed in PSCC cell lines and tumor samples, especially with the highest expression in corresponding metastatic lymph node tissues." (PMID 36151071, 2022). "HOXD11 was mediated by miR-138-5p and induced FN1 transcription and increased MMP2 and MMP9 expression to degrade ECM and promoted tumor metastasis in vivo and in vitro." (PMID 36151071, 2022). "Low expression of miR-138-5p in tumors leads to overexpression of HOXD11, which induced FN1 transcription and increased MMP2 and MMP9 expression to degrade ECM and promoted tumor metastasis in vivo and in vitro." (PMID 36151071, 2022). "More importantly, knockdown of FN1 also relieved the aggressiveness in HOXD11-overexpressing cells, indicating that FN1 was an essential and indispensable mediator in HOXD11-mediated PSCC tumor progression." (PMID 36151071, 2022). "To further elucidate the possible contribution of posterior HOXD genes to phenotype and tumor pathology of ES we analyzed contact dependent growth of HOXD10, HOXD11 and HOXD13 shRNA infectants with an impedance-based system." (PMID 27363011, 2016). "In contrast to DKK2, stable knock down of HOXD genes did not significantly influence bone invasiveness, although suppression of HOXD10, HOXD11 and HOXD13 seemed to slightly reduce the invasive growth potential of tumor cells in the bone marrow." (PMID 27363011, 2016). "Localization analysis of HOXD11 and OTP—selected for high expression abundance and consistency with in vitro validation—revealed predominant tumor-specific localization in paired tumor-adjacent samples (n = 2), while showing diffuse distribution in tumor-only samples (n = 2)." (PMID 41049291, 2025). "Collectively, these data suggested that HOXD11 might induce FN1 transcription by participating in ECM-mediated EMT and promoting tumor metastasis in PSCC." (PMID 36151071, 2022). "For each patient, HOXD10 and HOXD11 but not HOXB2 mRNA expression was gradually elevated in LM, PCA and N tissues, indicating the oncogenic potential of tumor aggressiveness in PSCC." (PMID 36151071, 2022). "When analyzing the frequency of detectable gene expression per tumor sample (presence/absence), no detectable expression of HOXA5 was observed in one case, while absence of amplification of either HOXD10 or HOXD11 transcripts was observed in two cases." (PMID 22227861, 2012). "To understand the downsteam mechanisms of HOXD11, we first analyzed the differentially expressed mRNA-seq between HOXD11-silenced Penl2 and negative control cells by functional enrichment analysis and found that EMT was involved in the tumor progression of PSCC." (PMID 36151071, 2022). "Interestingly, HOXD10, HOXD11 and HOXD13 knock down significantly decreased the number of TRAP+ cells within tumor tissue while their number in bones was not affected." (PMID 27363011, 2016).
cancer (14 papers, 2014 to 2025). A tumor composed of atypical neoplastic, often pleomorphic cells that invade other tissues. "HOXD11 may be involved in a variety of cancer-related cell signaling pathways such as cell cycle, DNA replication, ECM receptor interaction, and focal adhesion." (PMID 33614284, 2021). "Moreover, prior studies revealed oncogenic function of HOXA11, HOXA13, and HOXD11 in other cancers, implicating these genes in the pathogenesis of SEPN, although further studies will be needed to elucidate their role in this setting." (PMID 29383182, 2017). "For instance, the TSS of several developmental-related and cluster 2 genes, such as GATA4, HOXD11, and HOXD12, was hypermethylated in a variety of cancer types." (PMID 35580989, 2022). "The involvement of HOXD10, HOXD11, HOXD1, HOXC4, HOXC10, and HOXA11, in the cell cycle and the EMT, confirm their role in the cancer-related signaling pathways." (PMID 35562533, 2022). "HOXD11 and HOXD10, being homologous proteins, play distinct roles in cancer biology." (PMID 39428922, 2024). "Likewise, the buccal mucosa-derived H157 (RRID: CVCL_2468) cancer cell lines showed overexpression of HOXA10, HOXC6, HOXC9, HOXC10 and HOXD11 which was consistent with the cancer of the buccal mucosa." (PMID 35710803, 2022). "An association between germline mutations of four genes (FLT3, HOXD11, TCF3, and ATP1A1) and cancer has not been reported." (PMID 27701467, 2016). "The results showed that some HOX genes in pan-cancer had significant strong correlation (R≥0.8): HOXA9 with HOXA10, HOXB5 with HOXB6 and HOXB8, HOXB8 with HOXB6 and HOXB9, HOXB3 with HOXB4 and HOXB5 and HOXB6, HOXC8 with HOXC9, HOXC9 with HOXC10, HOXD10 with HOXD11." (PMID 39980564, 2025). "In addition, of all the 31 Onco/TSGs harboured sHyperMethyl and sHypoMethyl in their gene body, 7 genes (HOXD11, TAL1, HOXA9, PAX5, FOXP1, FOXO1, TERT) were reported to serve as potential DNA methylation-based biomarkers for non-invasive early cancer diagnosis." (PMID 37393582, 2023). "Analysis of DEHGs in oncogenic pathways using GSCALite26 indicated that HOXD10, HOXD11, HOXD1, HOXC4, HOXC10, and HOXA11 may have a crucial role in the activation of epithelial-mesenchymal transition (EMT) in cancer, represented in the form of heatmap percentage." (PMID 35562533, 2022).
HOXD11 also shares sentences with these, for which no sentence is quoted: breast carcinoma (4 papers); lung carcinoma (3); penile squamous cell carcinoma (3); hemangioblastoma (2); laryngeal squamous cell carcinoma (2); prostate carcinoma (2); acute myeloid leukemia (1); breast tumors (1); esophageal squamous cell carcinoma (1); leukemia (1); melanoma (1); Oral Squamous Cell Carcinoma (1); osteosarcoma (1); pancreatic cancer (1); teratoma (1).